CD24 (CD24 molecule)
Diseases named in the same sentence as CD24 in open-access papers (continued):
Sharing a sentence is not in itself a finding about the gene and the disease.
pancreatic cancer (continued). "Pancreatic cancer cells treated with GSI showed a significant reduction in CSCs with the ESA+/CD44+/CD24+ marker profile compared to untreated cells (2.76±0.16% control vs. 1.43±0.15% with GSI p = 0.013)." (PMID 24647545, 2014). "Pancreatic cancer stem cells (CSC) were first isolated from human pancreatic cancers using the marker profile ESA+/CD44+/CD24+." (PMID 24647545, 2014). "We identified a highly tumorigenic subpopulation of pancreatic cancer cells expressing the cell surface markers CD24, CD44 and ESA in pancreatic adenocarcinoma cell line PANC-1." (PMID 24521357, 2014). "Cancer Stem Cells (CSCs) of human pancreatic cancer cell line PANC-1 were processed for CD24, CD44 and ESA multi-colorstaining, and sorted out on a BD FACS Aria II machine." (PMID 24521357, 2014). "Pancreatic cancer cells with EMT phenotype displayed stem-like cell features characterized by the expression of cell surface markers CD24, CD44 and epithelial-specific antigen (ESA), which was associated with decreased expression of miR-200a." (PMID 24521357, 2014). "Consistent with our observations, a highly tumorigenic subpopulation of cells with CD44+/CD24+/ESA + phenotype was identified as cancer stem cells in pancreatic cancer." (PMID 24612587, 2014). "In summary, we identified a highly tumorigenic subpopulation of pancreatic cancer cells expressing the cell surface markers CD24, CD44 and ESA in pancreatic adenocarcinoma cell line PANC-1." (PMID 24521357, 2014). "Because CD133+ and CD24+CD44+ESA+ cells have been documented to be pancreatic cancer stem cells, we determined the effect of low concentrations of metformin on these subpopulations, demonstrating a decreased proportion of CD133+ cells." (PMID 23667692, 2013). "This phenomenon was also observed in the study conducted by Huang and coworkers, where CD44+/CD24+ pancreatic cancer cells showed an exacerbated tumorigenic potential." (PMID 23419168, 2013). "It was reported that CD44 is associated with FAK, paxillin, and Src activity, and the loss of CD24 expression significantly decreases cell proliferation, cell invasion, and metastasis nodules of CRC and pancreatic cancer in mice model." (PMID 23970932, 2013). "ARRs at physiologically achievable concentrations induce apoptosis of a number of pancreatic cancer cell lines as well as inhibit sphere formation by the CD44+/CD24+ stem-like cell population derived from the pancreatic cancer cell lines." (PMID 22570653, 2012). "In a genetically engineered mouse model disseminating pancreatic cancer cells are enriched for CD44+CD24+ CSC compared to the primary PanIN lesion or tumor, and have increased proliferation rates and spheroid formation capacity in vitro." (PMID 24213498, 2012). "In pancreatic cancer, cells based on specific cell-surface markers (i.e. CD24+CD44+ESA+ and CD133+ cells) have been reported to possess CSC characteristics." (PMID 22894607, 2012). "High expression of CD24 is involved in tumour progression and metastasis, while the intracellular studies in pancreatic cancer showed CD24 expression both on membrane surface and intracellular environment but inhibited the cell invasion and metastasis." (PMID 22693526, 2012). "We found however that spheres generated from CD44+/CD24+expressing pancreatic cancer cells also expressed CD133 as well as EpCAM." (PMID 22570653, 2012). "The CD44+CD24+ESA+ pancreatic cancer cells are highly tumorigenic and possess the stem cell-like properties of self-renewal and the ability to produce differentiated progeny." (PMID 21304978, 2011). "Here we characterized the malignant phenotypes of the pancreatic cancer stem CD44+/CD24+ cells, which were enriched under sphere forming conditions as analyzed by flow cytometry." (PMID 21673909, 2011). "These authors found minimal overlap between ALDH and CD44+/CD24+ cell populations (<0.1%), suggesting the existence of at least two distinct tumor-initiating populations within human pancreatic tumors." (PMID 21695188, 2011).
pancreatic cancer (continued). "ALDHhigh/CD44+/CD24+ cells comprised an average of 0.015% of all pancreatic cancer cells and ALDHlow/CD44+/CD24+ cells comprised 0.11% of all tumor cells." (PMID 21695188, 2011). "The elevation of GLI1 and GLI2 in holoclones suggests higher activity of Hedgehog signaling, which was consistent with the higher level of SHH expression in CD44+CD24+ESA+ cancer stem cells isolated from human primary pancreatic cancer specimens." (PMID 21826251, 2011). "Based on two independent reports, pancreatic cancer stem cells were identified as population of CD44+CD24+ESA+ or CD133+, however, these two populations showed little overlap with each other." (PMID 21826251, 2011). "This subpopulation of pancreatic cancer cells with CD44+/CD24+/ESA+ phenotype (only 0.2 to 0.8% of pancreatic cancer cells) had a 100-fold increased tumorigenic potential compared with other cancer cells." (PMID 19602232, 2009). "Both CD44 and CD24 positive pancreatic cancer cells are considered PCSCs43." (PMID 39897042, 2025). "CD24+ pancreatic cancer cell subpopulations exhibit the highest tumorigenic potential, indicating that they may be involved in the development of pancreatic cancer." (PMID 40486886, 2025). "Furthermore, co-targeting PARP1 (with talazoparib) and CD24 (with anti-CD24 mAb) elicited synergistic antitumor effects in human pancreatic cancer animal models (Fig. 3C2)." (PMID 37596619, 2023). "In pancreatic cancer, CSCs have been identified with the phenotype CD24+." (PMID 38137380, 2023). "Moreover, CD24 was reported to express in various other malignant conditions, including B-cell lymphomas, gliomas, lung, breast, urothelial tumors and pancreatic cancer and a second primary affecting the CD24 result cannot be excluded." (PMID 38138858, 2023). "Thus, the study suggests that DDX5 is involved in immune checkpoint molecule CD24-mediated resistance in pancreatic cancer." (PMID 37596619, 2023). "However, in pancreatic cancer cells, low expression of CD24 correlated with augmented adhesion to Matrigel, while elevated CD24 correlated with reduced adhesion." (PMID 35628262, 2022). "In pancreatic cancer, CD24 and CD44 are recognized as malignant CSC marker." (PMID 36430445, 2022). "Similarly, MEG3, an imprinted long non-coding RNA with tumor suppressor properties, decreased the number of CD44+/CD24+/ESA+ pancreatic cancer cells and the levels of Nanog and Oct4 expression." (PMID 34203589, 2021). "RPN2 is also highly expressed in the CD24+CD44+ cancer stem-like cells of pancreatic cancer." (PMID 33692975, 2021). "Moreover, tumor-initiating cells (TICs) isolated from pancreatic cancer patient positive for CSCs markers EpCAM+/CD44+/CD24+ display high CAIX expression." (PMID 32560271, 2020). "Through our ELISA assay we measured levels of different exosome populations, in particular those carrying the ubiquitous CD9, CD81 and some markers already found in tumour exosomes of pancreatic cancer such as CD44v6, Tspan8, EpCAM, CD24, CXCR4, Integrins α6 and β4, CD133." (PMID 31048929, 2019). "These authors have isolated CD44+CD24+ESA+ cells from xenografts in immunodeficient mice of pancreatic cancer cells and have shown that these cells are highly tumorigenic and regenerated into host immunodeficient mice the original tumor histology and heterogeneity." (PMID 29156578, 2017). "Besides, the enrichment of the CD44+CD24+ESA+ cells was observed after the ionizing radiation treatment in human primary pancreatic cancer xenografts." (PMID 28245823, 2017). "In addition, we show that CD24 protein is stabilized in response to WNT activation and that overexpression of CD24 in pancreatic cancer cells upregulated β-catenin expression augmenting an epithelial, non-metastatic signature." (PMID 27203385, 2016).
pancreatic cancer (continued). "The involvement of CD24 in the stabilization of an epithelial phenotype during pancreatic tumor development is supported by our in vivo experiments demonstrating that cells expressing surface CD24 generate exclusively differentiated tumors expressing β-catenin and lacking TWIST expression." (PMID 27203385, 2016). "CD24 has also been shown to be an important marker for pancreatic cancer stem cells." (PMID 27332878, 2016). "Pancreatic CSCs have been identified both in patient tumors by their expression of the cell surface markers ESA (epithelial surface antigen; CD326), CD44 and CD24 and in murine pancreatic tumors with a slightly different panel of markers (CD44+, CD133+, Sca1+)." (PMID 27330806, 2016). "Eventually, membranous CD24 augments the epithelial phenotype of pancreatic tumors." (PMID 27203385, 2016). "In general, a CD44+/CD24+ phenotype has stem-cell properties in pancreatic cancer cells." (PMID 27689400, 2016). "CD24 is expressed in many cancer types, including renal, ovarian, lung and pancreatic cancers." (PMID 26608463, 2015). "In general, a CD44+/CD24+/ESA+ phenotype has stem-cell properties in pancreatic cancer cells." (PMID 25118635, 2014). "For example, CD24+CD44+ESA+ pancreatic cancer cells possess CSC properties." (PMID 24955581, 2014). "This aggressive cell behavior was also demonstrated in CD44+/CD24+ pancreatic cancer cells." (PMID 23419168, 2013). "Also, ISIR-042 preferentially induced the cytotoxic effects on gemcitabine-resistant CD24+/CD44+ pancreatic cancer stem/progenitor cells from pancreatic cancer cell lines." (PMID 23301832, 2013). "To test the in vivo relevance of the tumorsphere experiments, we implanted equal numbers of Bmi1 silenced and control lentiviral transfected CD44+CD24+ESA+ CSCs derived from primary human pancreatic cancer xenografts in the subcutaneum of NOD/SCID mice and measured the resultant tumor growth." (PMID 23437065, 2013). "Later, CD44+/CD24+/ESA+ cells were referred to CSCs with 0.5%–1% of all pancreatic cancer cells." (PMID 22693526, 2012). "Interestingly, Pancreatic CD44+ESA+CD133+CD24+ CSCs also expressed CK19 (pancreatic cancer specific epithelial marker) and ABCG2 drug resistance genes." (PMID 23029396, 2012). "Previous studies have shown that pancreatic cancers and pancreatic cancer cell lines contain a small segment of cell population characterized by expression of CD133 or CD44/CD24/EpCAM positivity and which can be utilized to identify this cancer stem cell population." (PMID 22570653, 2012). "In addition, AHP3 and 3-Cl-AHPC inhibited growth and induced apoptosis in spheres derived from the CD44+/CD24+ (CD133+/EpCAM+) stem-like cell population isolated from the pancreatic cancer cell lines." (PMID 22570653, 2012). "The clinical relevance of targeting CSC-associated genes is supported by several recent studies, including CD44 targeting for treatment of acute myeloid leukemia, CD24 targeting for treatment of colon and pancreatic cancer, and CD133 targeting for hepatocellular and gastric cancer." (PMID 21317983, 2011). "Furthermore, the overexpression of GLI transcription factors has been correlated with elevated levels of CD24, a marker indicative of tumor-initiating cells (TICs), thereby contributing to the accumulation of CD24 within the subpopulation of pancreatic cancer stem cells." (PMID 40486886, 2025). "The treatment was effective even in CD24 subclone-bearing tumors, suggesting that targeting pancreatic cancer stem cells with the use of this approach could be a viable treatment strategy for the therapy of pancreatic cancer." (PMID 36013184, 2022). "However, when comparing the proteomics study of CD24+ pancreatic cancer cells enriched from patient material with our data generated from two human pancreatic cancer cell lines, there is a clear match at the level of pathways differentially regulated in CSCs and tumor bulk cells." (PMID 32503348, 2020).
pancreatic cancer (continued). "The intriguing observation that both CD133 positive and CD44+/CD24+ cells have been found to be tumor initiating cells and possess many of the characteristics of cancer stem cells suggests that heterogeneity exists in the pancreatic cancer stem cell population." (PMID 22570653, 2012). "The FITC-conjugated EpCAM antibody (green), PE-conjugated CD44 antibody (red), PE-conjugated CD24 antibody (red), and PE-conjugated CD133 antibody (red) were used to characterize the pancreatic cancer stem cells." (PMID 39843495, 2025). "Pancreatic cancer patients who received combined PARP1 and CD24 inhibition experienced a synergistic antitumor effect." (PMID 38279998, 2024). "By simultaneously blocking CD47 and CD24 signaling, PAC-SABI enhances the phagocytic ability of macrophages in vitro and in vivo, promoting anti-tumor responses in breast and pancreatic cancer mouse models." (PMID 38971872, 2024). "We measured the co-expression of CD24, CD44, c-Met, and CD326 to detect pancreatic cancer stem cells." (PMID 37308977, 2023). "The results showed that fisetin reduced the ratio of CD44+/CD24+ cells and increased that of CD44−/CD24− cells in human pancreatic cancer PANC1 cells." (PMID 37743465, 2023). "Putative CSCs have been identified in pancreatic cancer based on the expression of the three surface markers CD44, CD24, and epithelial specific antigen (ESA)." (PMID 37108495, 2023). "CD44 + CD24 + ESA + pancreatic cancer cells have been reported to exhibit significant resistance to GEM and radiation and contribute to pancreatic cancer recurrence and metastasis." (PMID 37737908, 2023). "In pancreatic cancer, although CD44+ cells themselves were more tumorigenic than CD44− cells, CD44+/CD24+/ESA+ cells had more stem cell-like characteristics than CD44−/CD24−/ESA− cells." (PMID 37108495, 2023). "PARP1 binds to, and inhibits DDX5 by ADP-ribosylating DDX5 in pancreatic cancer cells (Fig. 3C1), which can be abolished by PARP1 inhibitor, talazoparib, while PARP1 inhibition increased DDX5 expression and binding to the CD24 promoter." (PMID 37596619, 2023). "In pancreatic cancer, CSCs were first reported in 2007 as a subpopulation of CD44(+)/CD24(+)/ESA(+) or CD133(+)/CXCR4(+) cancer cells, and many CSCs have been identified using these three methods." (PMID 35629168, 2022). "Next, we investigated the combined effect of CD24, CD44, and SLC16A1 expression on the prognosis of the pancreatic cancer patients." (PMID 36302783, 2022). "Those cells expressing CD44+, CD24+, and ESA (named pancreatic cancer stem cells) were responsible for tumor formation." (PMID 35800881, 2022). "In this study, surface marker expressions for the pancreatic cancer stem cell-like population, namely CD44, CD24, and ESA for Panc1 cells and CD44, CD133, and EpCAM in MiaPaCa2 cells were investigated." (PMID 35634239, 2022). "Dual CD24 inhibition with SWA11 and ML-5 suppressed the proliferation of CD24+ pancreatic cancer cell lines, with the antiproliferative effect correlating with CD24 expression levels." (PMID 36013184, 2022). "In pancreatic cancer cells, GLRX3 was increased in spheres compared to adherent cells and was also increased in CD24+/CD44+/ESA+ cells compared to CD24−/CD44−/ESA- cells." (PMID 34794402, 2021). "Of xenograft cells receiving gemcitabine treatment, 32% were CD24+ CD44+ ESA+ cells, compared with 0.8% of control pancreatic cancer cells receiving vehicle treatment." (PMID 33995647, 2021). "In human pancreatic cancers, CD44+CD24+ESA+ cells have been found to be enriched for cancer stem cells (CSCs) verified by testing the tumor initiating capability of those cells in vivo." (PMID 33924486, 2021). "Confocal microscopy revealed that these PANC-1 CSC pancreatic cancer spheroids were labeled with antibodies against CD44, CD24, EpCAM." (PMID 34885233, 2021).
pancreatic cancer (continued). "Pancreatic cancer spheres were mechanically dissociated into single cells in a special cell disaggregation medium and sorted for CD44+CD24+EpCAM+ cells by means of flow cytometry." (PMID 34885233, 2021). "The same scenario happened in CD24/44 stem cell system in PanIN/IPMN, which was reported as pancreatic cancer stem cell (CSC) markers, CD24/CD44 population decreased significantly in IPMN than in PanIN when treated with Akti." (PMID 32266133, 2020). "Compared with the CD24+ subpopulation, the CD133+ subpopulation is a very small portion of the total number of pancreatic cancer cells." (PMID 30728024, 2019). "In pancreatic cancer, cells that express the cell-surface proteins CD13339 or the combination of CD44/CD24/EpCAM40 have been shown to exhibit characteristics of stem cells." (PMID 31101868, 2019). "The subpopulations of pancreatic cancer cells that express CD44 and CD24 display CSC-like properties." (PMID 29179494, 2017). "They compared the tumorigenicity of different sets of primary tumor cells and identified that c-Met high cancer cell population had the highest tumorigenic potential, compared with pancreatic cancer cells expressing CD44, CD24, ESA and CD133." (PMID 28245823, 2017). "In our study, we characterized two pancreatic cancer cell lines (MIA PaCa-2 and PANC-1), using the expression of reported CSC surface markers including CD44, CD24, ESA, and CD133." (PMID 29179494, 2017). "Both CD24 and ALDH1A1 expression levels were elevated in CTCs compared to leucocytes and pancreatic cancer cell-line cells." (PMID 28569190, 2017). "Pancreatic cancer stem cells had been initially identified in 2007 by Li and coworkers who investigated the expression of CD44, CD24 and epithelial-specific antigen (ESA) in pancreatic tumors." (PMID 29156578, 2017). "Sorted pancreatic tumour cells ALDH-positive, dual CD24- and CD44-positive, and triple CD24-, CD44-, and ALDH-positive were previously demonstrated to be highly tumourigenic compared to unsorted tumour cells." (PMID 28569190, 2017). "Pancreatic CSCs express specific markers, including CD24, CD44, CD133, EpCAM, CXCR4, c-Met, and CD166, at levels substantially different from the bulk pancreatic cancer cells." (PMID 28845161, 2017). "Evidence from recent work suggests that pancreatic cancer comprises several subsets of CSCs, including ESA+CD24+CD44+ cells, CD133+CXCR4+ cells, and c-Met+ subset cells, which are defined by their self-renewal ability, tumorigenicity, and metastatic ability." (PMID 28032597, 2017). "CD44+CD24+EpCAM+, CD133+, ALDH+ are markers for prospectively identifying pancreatic cancer stem cells." (PMID 26673007, 2016). "To address the expression of the putative CSC markers CD24, CD44, EpCAM, CD133, and nestin in pancreatic cancer, we used three cell lines (P6B, P28B, and P34B) derived from PDAC tumor tissues and three corresponding FFPE tumor samples." (PMID 27414409, 2016). "Real-time PCR and flow cytometry confirmed that FH535 downregulated CD24 and CD44, pancreatic cancer stem cell (CSC) markers, suggesting FH535 impairs pancreatic CSC stemness." (PMID 27323403, 2016). "CSC populations at basal level were detected in PANC-1 cells using multi-fluorescence labeled flow cytometry to identify CD24+CD44+EpCAM+ cells, as these cellular surface markers were indicative for pancreatic cancer stem cells." (PMID 27764163, 2016). "Several cell-surface markers, including CXCR4, ALDH, CD24 and CD44 have been used to identify of cancer stem-like cells in pancreatic cancer." (PMID 25811929, 2015). "Researchers usually identified CSCs from pancreatic cancer based on the expression of the cell surface antigens like CD44, CD24, epithelial-specific antigen (ESA), and CD133." (PMID 24489910, 2014). "Subsequently, CD133, CD44, CD24 were selected as CSC markers in many solid tumors, including pancreatic carcinoma." (PMID 24689055, 2014).